MUTYH (mutY DNA glycosylase)
Diseases named in the same sentence as MUTYH in open-access papers (continued):
Sharing a sentence is not in itself a finding about the gene and the disease.
colorectal adenoma (21 papers, 2009 to 2026). An adenoma that arises from the colon or rectum. "MUTYH-deficient familial colorectal adenomas are globally hypomethylated compared with MUTYH-proficient ones, supporting a possible role of MUTYH in addition to OGG1 in the regulation of mC epigenetic status." (PMID 41465236, 2025). "By ES, a frameshift variant of MUTYH, c.1101dupC, p.(Arg368Glnfs*164), was present in three individuals (ID 47, 534, and 535) out of four with colorectal adenomas or carcinoma from the Chilean family PAF20 and affected two generations." (PMID 36387175, 2022). "The elevated mutation rate in normal intestinal epithelium likely contributes to the increased risk of colorectal adenomas and cancers in individuals with MUTYH mutations." (PMID 35803914, 2022). "This study aimed to identify the germline mutations in MUTYH gene and determine their prevalence among Jordanian patients with colorectal adenoma." (PMID 31104418, 2019). "In conclusion, germline mutations in MUTYH gene are highly prevalent among patients with colorectal adenoma from Jordan." (PMID 31104418, 2019). "MUTYH germline mutations have been linked to multiple colorectal adenomas inheritance in Caucasian populations." (PMID 31104418, 2019). "Supposing that Jordanian patients with colorectal adenoma have a novel germline mutation(s) in MUTYH gene, this study aimed to identify these mutations among those patients and to determine their prevalence in relation to their ethnic background." (PMID 31104418, 2019). "Further investigation led to the identification of seven other unrelated patients with colorectal adenomas or carcinomas that showed a bias of CG→AT transversion mutations to be carriers of biallelic germline mutations for MUTYH." (PMID 23450852, 2013). "MAP is a disorder caused by bi-allelic germline MUTYH mutations, characterized by multiple colorectal adenomas." (PMID 20687945, 2010). "Recently, biallelic mutations in MUTYH have also been identified in patients with multiple colorectal adenomas and in APC-negative patients with FAP." (PMID 19531215, 2009). "Inherited biallelic MUTYH mutations cause predisposition to colorectal adenomas and carcinoma." (PMID 35803914, 2022). "The data showed high prevalence of two germline mutations in MUTYH gene among Jordanians with colorectal adenoma, which may make them as potential early biomarkers for diagnosis of colorectal adenoma." (PMID 31104418, 2019). "Finally, the existence of genes, other than APC and MUTYH, susceptible to colorectal adenomas and cancer cannot be excluded." (PMID 20649969, 2010). "Colorectal adenomas and carcinomas from individuals with MAP show a predominance of C > A mutations consistent with the presence of an elevated mutation rate attributed to defective MUTYH function." (PMID 35803914, 2022). "However, in the present study, MUTYH gene was sequenced thoroughly for the patients with colorectal adenoma and the controls from the same ethnic group." (PMID 31104418, 2019). "Moreover, we observed evidence that SNPs in other BER genes modified the effect of smoking (MUTYH, OGG1), alcohol (LIG3), and dietary folate (LIG3) on colorectal adenoma risk." (PMID 23951112, 2013). "Genetic testing for MUTYH mutation has been recommended for all patients who have tens to hundreds of colorectal adenomas with no identified germline mutation in the APC gene and with a family history compatible with an autosomal recessive mode of inheritance." (PMID 19822006, 2009). "Recently, patients with multiple colorectal adenomas and also patients with FAP but without detectable germline APC mutations have been found to carry biallelic mutations in the base-excision-repair gene MUTYH (MYH)." (PMID 19531215, 2009).
colorectal polyposis (16 papers, 2010 to 2024). "The cumulative results of recent screenings of colorectal polyposis patients for MUTYH mutations have revealed many MUTYH gene variants, but the repair activity of the type 2 protein of most of the variants has never been tested." (PMID 20848659, 2010). "APC and MUTYH are both well-known colorectal polyposis causative genes." (PMID 38647838, 2024). "MUTYH mutations predispose to recessively inherited colorectal polyposis and cancer." (PMID 22297469, 2012). "Moreover, mutations in the MUTYH gene are known to predispose patients to the development of both colorectal polyposis and cancer; however, our hypothesis suggests that they may be less susceptible to AD with efficient care for carcinogenesis." (PMID 34970419, 2021). "To gain insight into the role of altered gene expression in hereditary colorectal polyposis predisposition, in the present study we analyzed absolute and allele-specific expression (ASE) of adenomatous polyposis coli (APC) and mutY Homolog (MUTYH) genes." (PMID 26511139, 2015). "A significant group of patients with multiple colorectal polyps remains genetically unexplained after extensive testing for pathogenic APC and MUTYH variants." (PMID 25604157, 2015). "Moreover, biallelic mutations in mutY homolog (MUTYH) gene were found to be associated, with an autosomal recessive pattern of inheritance, in a colorectal polyposis referred as MAP (MUTYH-associated polyposis)." (PMID 29954149, 2018).
hereditary cancer (14 papers, 2014 to 2026). Malignant neoplasms occurring in families at a rate greater than that expected by chance and caused by germline mutations in a specific gene. "It is interesting to consider that the pathogenic mutations in MUTYH associated with hereditary cancer have been mostly reported in homozygosity, with the complete inactivation of its product." (PMID 38074417, 2023). "Most notably, defects in repair of one of the most abundant oxidative DNA lesion, 8-oxo-deoxyGuanine (8-oxo-G), are implicated in familial cancer syndromes involving mutations in the DNA glycosylases MutY homolog (MUTYH) or 8-oxoguanine DNA-glycosylase 1 (Ogg1)." (PMID 27258260, 2016). "Analysis of hereditary cancer cases (732 BC patients, 189 CRC patients, and 490 cancer-free elderly controls) revealed that 1% presented concurrent germline pathogenic variants in BRCA1, BRCA2, MUTYH, ATM, CHECK2, NBN, and RAD50." (PMID 37628631, 2023). "The majority of germline alterations were unknown or benign, with the exception of one alteration each in familial cancer genes MUTYH, CHEK2, and FANCL, as well as one germline alteration in ID3." (PMID 36232827, 2022).
juvenile polyposis syndrome (13 papers, 2013 to 2025). Juvenile gastrointestinal polyposis (JIP) is a rare condition characterized by the presence of juvenile hamartomatous polyps in the gastrointestinal (GI) tract. "Other rare colonic polyposis syndromes for which the genetic basis is known include Cowden syndrome (mutations in PTEN), juvenile polyposis (mutations in SMAD4 or BMPR1A), hereditary mixed polyposis syndrome (mutation in GREM1), and MUTYH-associated polyposis (biallelic mutations in MUTYH)." (PMID 23805267, 2013).
endometrial cancer (12 papers, 2009 to 2025). Primary or metastatic malignant neoplasm involving the endometrium (mucous membrane that lines the endometrial cavity). "Biallelic MUTYH mutations have been found in patients affected with endometrial carcinoma, and a few reports indicated a possible relationship with endometrial cancer." (PMID 30886832, 2019). "In addition to MUTYH, there were another five genes which were identified with germline variants in patients with endometrial cancer." (PMID 30886832, 2019). "Our pilot study has shown that a second somatic MUTYH hit is an unlikely pathogenetic mechanism in monoallelic carriers with breast, ovarian and endometrial cancer." (PMID 38790183, 2024). "At present there is little information about the role of MUTYH in other types of cancer and only one report indicating a possible relationship with endometrial cancer." (PMID 19338676, 2009). "The high frequency of BC and endometrial cancers observed in our patients is in line with the findings of these studies, further supporting the hypothesis that MUTYH dysfunction may contribute to tumorigenesis at extra‐colon sites." (PMID 41001951, 2025). "The results of our study suggest that MUTYH is unlikely to be involved in the genetic basis of endometrial cancer but a possible association of MUTYH variants with HNPCC related diseases cannot be excluded." (PMID 19338676, 2009). "Given the fact that MUTYH is a recessive gene, MUTYH-monallelic-PV could not explain the cancer phenotype; in contrast, several recent studies support the possible role of monoallelic mutations in MUTYH conferring risk for colorectal, breast, gastric and endometrial cancer." (PMID 32522261, 2020).
gastric cancer (10 papers, 2008 to 2024). A primary or metastatic malignant neoplasm involving the stomach. "Carriers of bi- and monoallelic MUTYH mutations are also at higher risk for the development of gastric polyps and gastric cancer." (PMID 37568604, 2023). "However, the great majority of MBC patients with MUTYH pathogenic variants had family history of cancer, including, breast, colorectal, and gastric cancers." (PMID 30564557, 2018). "Therefore, patients with sporadic gastric cancer with SBS18 could be further evaluated for MUTYH mutational status or base excision and homologous repair deficiency to assess responsiveness to targeted therapies with inhibitors." (PMID 37568604, 2023). "Gastric cancer is one of the extracolonic manifestations of MAP, found in patients with MUTYH biallelic mutations." (PMID 29954149, 2018).
melanoma (10 papers, 2017 to 2025). A malignant, usually aggressive tumor composed of atypical, neoplastic melanocytes. "MUTYH variants have not been linked to melanoma previously and although MUTYH is generally considered a recessive tumor suppressor gene it is known that individuals heterozygous for disruptive MUTYH alleles are at greater risk of developing a range of cancers." (PMID 30664638, 2019). "However, bi-allelic and mono-allelic carriers of MUTYH mutations are not known to be at risk of melanoma, renal or thyroid carcinoma." (PMID 30233642, 2018). "As for MUTYH and MAP3K4, there is only evidence in literature for treatment of degenerative diseases (MUTYH) and melanoma (MAP3K4)." (PMID 34316711, 2021).
pancreatic cancer (10 papers, 2017 to 2025). "Germline MUTYH mutations have previously been identified in patients with pancreatic cancer; however, further clinical studies are necessary to determine the risks in cancer development." (PMID 38201513, 2023). "In the past few years, monoallelic MUTYH PVs have been found in patients with gastric, liver, endometrial, breast, ovarian and pancreatic cancer, and this has led to several studies investigating the impact of germline monoallelic MUTYH PVs in tumorigenesis." (PMID 36292577, 2022). "Patient 3 presented with bilateral BC at 47, her mother died from pancreas cancer, her maternal grandmother had CRC, her paternal grandmother had BC; she had the MUTYH c.536A>G (p.Tyr179cys), but also a mutation in CHEK2: c.470T>C (p.Ile157Thr) that is known as pathogenic." (PMID 41001951, 2025).
glioma (9 papers, 2016 to 2026). A benign or malignant brain and spinal cord tumor that arises from glial cells (astrocytes, oligodendrocytes, ependymal cells). "Integrating previous studies, we summarized germline MUTYH mutations in 11 cases of high-grade neuroepithelial tumors (eight gliomas and three medulloblastomas)." (PMID 40469416, 2025). "Integrating previous studies, we summarized a total of 11 high-grade glioma cases with germline MUTYH mutations." (PMID 40469416, 2025). "While our study identified germline MUTYH mutations in a subset of glioma patients, the small sample size precluded definitive conclusions about causality or independence from confounders." (PMID 40469416, 2025). "Integrating previous studies, we analyzed germline mutations of MUTYH in 11 patients with high-grade gliomas." (PMID 40469416, 2025). "In a study of 152 glioma patients, germline pathogenic MUTYH variants were detected in about 0.5% of patients." (PMID 38790183, 2024). "Considering that in other CNS tumors tested by our group, MUTYH mutations occur very sparsely, we contribute with two novel cases to the establishment of the association between germline mutations of MUTYH and gliomas, especially H3‐mutated entities." (PMID 35545820, 2022). "Together with a single previous report, our data raises the possibility of an association between germline MUTYH mutations and CNS malignancies, particularly in pediatric histone H3‐mutant gliomas." (PMID 35545820, 2022). "Here we present two cases of high‐grade pediatric glioma harboring H3‐3A G34V and H3‐3A K27M mutations, respectively, in association with germline, inherited, heterozygous MUTYH mutations." (PMID 35545820, 2022). "The potential mechanism linking MUTYH mutations to histone‐mutant or other types of high‐grade gliomas cannot be characterized on the basis of current knowledge." (PMID 35545820, 2022). "We present early treatment outcomes with glioma-based therapies and identify the first documented MUTYH mutation in these tumors, which may provide valuable insights into CNS tumorigenesis." (PMID 40575153, 2025). "Together with the previous report of a H3 K27M‐mutant midline glioma in association with MUTYH mutation, our H3 K27M‐ and H3 G34V‐mutant cases suggest a potential link between pediatric gliomas and MUTYH mutations and expand our knowledge on the pathogenesis of these tumors." (PMID 35545820, 2022).
hereditary cancer syndrome (9 papers, 2016 to 2025). "Fifteen percent of patients in this study had a hereditary cancer syndrome designated by an inherited PGV, of which 2.5% (7 of 284) were heterozygous for MUTYH and have an unclear cancer risk." (PMID 34830767, 2021).
lung carcinoma (9 papers, 2004 to 2025). "Following DNA isolation from 326 lung cancer and 330 normal control cases and subsequent genotyping, the group found that single allelic carriers (Gln324His) for the MUTYH gene increased risk of overall lung cancer susceptibility." (PMID 31027119, 2019). "Case–control analysis showed SBDS c.184A>T(p.K62*), TSHR c.1574T>C(p.F525S), BRIP1 (BRCA1 interacting helicase 1) c.1018C>T(p.L340F), and MUTYH (mutY DNA glycosylase) c.55C>T(p.R19*) were significantly associated with increased lung cancer risk (q value < 0.05)." (PMID 37885353, 2024). "This suggested that MUTYH Gln324His might also be associated with risk for lung cancer, related to the decreased MUTYH enzyme activity." (PMID 19161591, 2009). "In different histological types of lung cancer, MUTYH His/His genotype was a significantly borderline association for both adenocarcinoma and squamous cell carcinoma, that suggested a potential interaction between this polymorphism and lung cancer risk regardless these subtypes." (PMID 19161591, 2009). "Herein, we report that gene polymorphisms, OGG1 Ser326Cys and MUTYH Gln324His, of two DNA repair genes in the BER pathway can modulate lung cancer risk in a small case-control study." (PMID 19161591, 2009). "Previous study has shown that the identified variants of the MUTYH gene, containing Gln324His, were unlikely to predispose significantly to the risk for lung cancer in Caucasians." (PMID 19161591, 2009). "Similarly, germline variants in MUTYH have been linked to an increased risk of lung cancer, particularly in non-smokers." (PMID 40430005, 2025). "However, there have been no previous reports on OGG1, MUTYH, and APEX1 with regard to survival in lung cancer." (PMID 23443124, 2012).
prostate carcinoma (9 papers, 2018 to 2024). A carcinoma that arises from epithelial cells of the prostate gland. "Monoallelic pathogenic MUTYH variants were also reported in patients affected by prostate cancer, with a frequency of about 0.5–1%." (PMID 38790183, 2024). "In the last years, several studies also investigated the impact of germline monoallelic MUTYH pathogenic variants in genetic susceptibility to the development of BC, OC, or prostate cancer, showing increased risk rates associated with heterozygosity." (PMID 39684352, 2024). "Emerging data has also linked several germline DNA mutations to prostate cancer, namely BRCA1, BRCA2, MSH, ATM, PALB2, CHEK2, and MUTYH." (PMID 32957584, 2020). "GJB2, MET, MUTYH and VHL mutations ranked top in kidney cancers, and ATM and CHEK2 mutations ranked top for bladder cancer, while ATM and BRCA1 mutations ranked top for prostate cancer." (PMID 36451132, 2022).
pancreatic neuroendocrine tumor (8 papers, 2017 to 2024). Pancreatic endocrine tumor, also known as pancreatic neuroendocrine tumor (PNET), describes a group of endocrine tumors originating in the pancreas that are usually indolent and benign, but may have the potential to be malignant. "This allele of MUTYH has also been associated with MUTYH loss of heterozygosity in certain pancreatic neuroendocrine tumors, indicating that the allele is a recessive tumor suppressor." (PMID 34680217, 2021). "Furthermore, MUTYH/CHEK2, BRCA2, CDKN2A, and TIMP3 have also been associated with pancreatic neuroendocrine tumors." (PMID 35163032, 2022). "Interestingly, a recent report on a related disease, pancreatic neuroendocrine tumors (PAN-NETs), has described mutations in the MUTYH gene." (PMID 28634180, 2017).
hereditary colorectal cancer (7 papers, 2013 to 2025). "Bi‐allelic inherited mutations in MUTYH, the base excision repair (BER) enzyme eliminating adenine paired to 8‐OHdG have been found in patients with hereditary colorectal cancer." (PMID 26899729, 2016).